CGAS (cyclic GMP-AMP synthase)
Diseases named in the same sentence as CGAS in open-access papers (continued):
Sharing a sentence is not in itself a finding about the gene and the disease.
tumor (continued). "Thomsen suggested that modulation of the cGAS-STING pathway could affect the tumor progression of HCC, and potentially be used as a treatment in patients with HCC." (PMID 33006365, 2020). "Therefore, further elucidation of what switches cGAS-STING signaling between tumor prevention and activation will be important if this pathway is to be used therapeutically." (PMID 33230251, 2020). "Moreover, the previous studies of cGAS–STING signaling in cancer are largely focused on tumor cells." (PMID 32382015, 2020). "However, emerging evidence suggested the pro-tumor roles of the cGAS-STING pathway, from tumor initiation and development, to metastasis, which makes the application of STING agonists in the clinic remains a lot to challenge." (PMID 32571374, 2020). "It has been reported that cGAS and STING expression is suppressed by methylation in a pan-tumor analysis, indicating the possibility that cGAS and STING might be inhibited by DNMT1." (PMID 32296457, 2020). "Prolonged cGAS-STING activation within the TME (> 5 h) causes cytokine levels to remain high within the tumoral and tumor-draining lymph nodes (TDLN), and it is unclear whether this is due to direct or indirect STING activity." (PMID 32774773, 2020). "This suggests that caspase 9 suppresses tumor-intrinsic DNA sensing involving cGAS–STING." (PMID 33238631, 2020). "Interestingly, NK cells, lymphocytes and macrophages are all important mediators of anti-tumor immunity downstream of cGAS-STING activation, depending on the immunogenicity of the specific tumor." (PMID 32774773, 2020). "Emerging evidence reveals that the cGAS-STING signaling cascade may have dichotomous effects on tumor development." (PMID 32854711, 2020). "The cGAS-STING pathway thus seems to have a tumour suppressive as well as a tumour-promoting role." (PMID 32873156, 2020). "T cell-mediated anti-tumor response may also be induced by cytosolic DNA from dying tumor cells through the activation of cGAS/STING-mediated type I IFN production." (PMID 32486257, 2020). "Another paper has found that tumoral cGAS and host STING expression, specifically, are critical for an NK cell-mediated tumor rejection response, suggesting a complex interplay between both host and tumoral cGAS-STING signaling in mediating the downstream anti-tumor immune response." (PMID 32774773, 2020). "In addition to these, tumor-derived DNA has been demonstrated to induce IFN-β production via cGAS-STING-IRF3 axis, contributing to spontaneous T cell- and natural killer cell mediated-anti-tumor responses." (PMID 32174922, 2020). "Furthermore, patients in advanced stages and tumor grades of HCC had higher mRNA expression levels of cGAS-STING pathway members compared with those in early stages of the disease." (PMID 33006365, 2020). "The function of the cGAS-STING signaling pathway is identified in several mouse tumor models." (PMID 32887628, 2020). "cGAS–STING signaling was recently demonstrated to be critically involved in tumor development." (PMID 32382015, 2020). "In the tumour context, the cGAS/STING pathway appears to be the major innate immune DNA sensing pathway that drives dendritic cells (DCs) activation and subsequent T-cell priming against tumour-associated antigens in vivo." (PMID 33121210, 2020). "The cGAS-STING pathway is now also recognised as a crucial mechanism regulating tumour immunity." (PMID 33081170, 2020). "cGAS may exert tumor suppressive effect by providing additional barriers for premalignant cells that are exposed to chronic DNA damage or have mutations in oncogenes or tumor suppressor genes." (PMID 32541866, 2020). "The activation of the cGAS-STING pathway plays a crucial role in both tumor cells and immune cells as an innate immune sensor, which could regulate multiple steps in cancer-immunity cycle." (PMID 32571374, 2020).
tumor (continued). "It is found that tumor cell‐free microparticles as an ideal vaccination platform can effectively transfer the tumor DNA fragment to DCs and lead to robust antitumor immunity, which is mediated by the cGAS‐STING signaling pathway." (PMID 33377643, 2020). "Consequently, molecular cGAS prevents homologous‐recombination‐mediated repair and advances tumor development, and that cGAS, in this manner, speaks to a potential objective for cancer counteractive immunotherapy." (PMID 32195086, 2020). "Similar to exogenous DNA damage, inherent DNA repair defects in tumours may also increase the production of cytosolic DNA and appear to similarly trigger a cGAS-STING response." (PMID 32283785, 2020). "Although the downregulation or silencing of cGAS-STING within tumor cells might limit host anti-tumor immunity, it is precisely this mechanism that also renders the cells more susceptible to viral oncolysis." (PMID 32774773, 2020). "cGAS is crucial for cytosolic DNA sensing. cGAS Acute activation of cGAS has been shown to lead to tumor regression in mice, whereas chronic cGAS activation may lead to inflammation-induced tumorogenesis." (PMID 32226386, 2020). "Moreover, emerging evidence suggested the pro-tumour roles of the cGAS-STING pathway in cancer progression, thus, limiting the application of STING agonists in the clinic." (PMID 33121210, 2020). "Anti-PD-L1 exhibits a tumor inhibition effect in wild-type mice but not in mice deficient in cGAS or STING." (PMID 32992835, 2020). "As it turns out, although the cGAS-STING pathway has clear anti-tumor benefits [i.e., stimulating immune cell-mediated clearance of (pre-) malignant cells], chronic cGAS-STING activation due to the persistence of cytosolic DNA causes the opposite effect, inflammation-mediated tumorigenesis." (PMID 32774773, 2020). "Additionally, cGAS plays critical roles in tumor metastasis, antitumor response via immune checkpoint blockade, and DNA repair, which offer enhanced tumor immunosurveillance, combinatorial therapeutics, and hold promise for successful cancer immunotherapy." (PMID 32195086, 2020). "Activation of the cGAS-STING pathway in tumor cells may pose an obstacle to the progression of early neoplastic cells by upregulating type I IFNs or other inflammatory genes." (PMID 32571374, 2020). "Further study in mouse model demonstrated that downregulated cGAS-STING pathway led to decreased tumor-infiltrating CD3+ CD8+ T cells by reducing the expression of downstream genes of type I IFN such as chemokine (C-X-C motif) ligands 9 and 10 (CXCL9 and CXCL10)." (PMID 30935414, 2019). "Furthermore, STING deficient mice fail to reject tumor after local radiation highlighting the importance of the cGAS-STING signaling pathway in RT tumor immunity." (PMID 30895168, 2019). "This is exemplified by a study showing that the PD-L1 inhibitors failed to give any anti-tumor effect in in cGAS deficient mice." (PMID 31658669, 2019). "Its significance in antitumor immunity was brought to attention by in vivo experiments where mice deficient in STING or cGAS (cyclic GMP-AMP synthase), an upstream component of the pathway, failed to reject tumor growth." (PMID 31535086, 2019). "Notably, advances of immunotherapy provide multiple feasible approaches to reprogram tumor immune microenvironment together with cGAS-STING agonist." (PMID 30935414, 2019). "We proposed that cGAS-STING-induced type I IFN might promote the survival of memory tumor-specific CTLs." (PMID 30935414, 2019). "Collectively, these results suggest that niraparib induced cGAS/STING activation in tumor cells, which may play a role in tumor-intrinsic type I interferon induction." (PMID 30755715, 2019). "A growing body of evidence indicates that a cocktail of cGAS-STING agonist together with immunotherapy could effectively eradicate tumor mass and induce durable anti-tumor immune response." (PMID 30935414, 2019).
tumor (continued). "In addition, it has become clear that innate immune STimulator of Interferon Genes (STING) signaling through the cGAS-STING complex plays a vital role in directing T cell responses toward infected tumor cells." (PMID 30619273, 2018). "Furthermore, tumor-derived MVs have been shown to activate DCs in vivo by delivering tumor DNA triggering intracellular signaling cGAS/STING pathway resulting in potent anti-tumor responses." (PMID 30455687, 2018). "Following IR, the tumor microenvironment undergoes changes including an increase in DNA damage followed by enhancement of the DNA sensing pathway via cGAS/STING, which leads to an increase in type I interferon production and signaling, and a subsequent, powerful adaptive immune response." (PMID 29170400, 2017). "They showed a large increase of tumor-infiltrating leukocytes in wild-type mice after PD-L1 antibody treatment, but not in cGAS- or STING-deficient mice." (PMID 29050360, 2017). "The dying tumor-derived DNA after treatment with radiation or antibody to CD47 is delivered to the cytoplasm of DCs to activate the cGAS-STING pathway and induce IFNs production, further bridging the innate and adaptive responses, which is represented by the activation of CD8+ T cells." (PMID 28216575, 2017). "Likewise, abscopal responses were dependent on the expression of cGAS by TSA cells in the irradiated tumour." (PMID 28598415, 2017). "cGAS-mediated type I IFN production is also essential for tumor surveillance." (PMID 27696330, 2016). "Considering the role of cGAMP in STING pathway, we proposed that cGAMP might activate anti-tumor immunity through cGAS-cGAMP-STING-IRF3 innate immune pathway." (PMID 26754564, 2016). "Elevated stiffness, nevertheless, suppresses tumor immunogenicity by activating the Rho-associated coiled-coil kinase-non-muscle myosin heavy chain IIA-filamentous actin pathway in tumor cells, which inhibits cGAS-STING pathway activation and consequently reduces DC differentiation." (PMID 41362727, 2026). "Like in ecDNA+ human tumor cells, ectopic expression of cGASWT in CT1BA5-EC cells produced cGAMP, although to a level lower than the histone-binding-deficient mutant cGASR236E, but substantially higher than the cGAMP level in CT1BA5-HSR cells that express similar levels of WT cGAS (p = 0.0025)." (PMID 41509453, 2026). "Hence, by suppressing MYC oncogenes, encouraging activation of cGAS‐STING pathway may help to sensitize tumour to PD‐L1‐targeted immunotherapy." (PMID 41492185, 2026). "Thus, the pharmacological targeting of the ferroptosis-cGAS -STING pathway may serve as a novel therapeutic strategy for tumor treatment." (PMID 40846966, 2025). "Additionally, modifications that improve the dispersion and stability of LNPs under physiological conditions may facilitate enhanced tumor cell uptake and promote the activation of the cGAS-STING pathway." (PMID 40831989, 2025). "Future mechanistic studies exploring the impact of DNA sensing by different cell types in a tumor via the cGAS-IFN-I pathway on DC and CD8+ T-cell functions, as well as on cancer cell immunogenicity, may lay the foundation for modulating this pathway to achieve effective cancer control." (PMID 40282455, 2025). "In addition to recruiting immunosuppressive γδ T cells, cGAS/STING activation has been shown to enhance tumor cell killing by upregulating multiple proinflammatory cytokines, principally IFN, and upregulating costimulatory molecules required for antigen presentation." (PMID 41392975, 2025). "Furthermore, radiotherapy can also promote anti-tumor immunity by activating immune pathways in tumor microenvironment (for example, cGAS-STING induces type I interferon response), thus providing a theoretical basis for the combined application of sensitizer and immunotherapy." (PMID 41516303, 2025). "Additionally, cGAS‐independent NC‐STING activation demonstrates tumour‐suppressive functions." (PMID 41275427, 2025).
tumor (continued). "Furthermore, anti-tumor immunity is dependent on the cGAS-STING cytosolic DNA sensing pathway." (PMID 40699783, 2025). "Mechanically, with higher precise radiation dose, SRT may be more effective in inducing immunogenic cell death and remodeling tumor immune microenvironment, through powerful immune-modulatory pathways, such as cGAS/STING signaling, VEGF/VEGFR signaling, COX2/IDO1 signaling." (PMID 40748918, 2025). "However, activation of cGAS‐STING in the tumor microenvironment (TME) may result in further complications." (PMID 40568953, 2025). "Additionally, there is a growing interest in understanding the role of the cGAS-STING pathway in non-neoplastic diseases, which may reveal new opportunities for the application of both STING agonists and inhibitors." (PMID 40008133, 2025). "However, whether ciprofloxacin mediates the cGAS-STING signaling pathway to suppress tumor growth remains unknown." (PMID 40643531, 2025). "Moreover, Zn2+ overload in tumor cells accelerated by NIR light could also further enhance the enzymatic activity of cGAS through the metal immunity effect." (PMID 40486836, 2025). "This includes not only serum and immune biomarkers but also tumor-intrinsic biomarkers of immune competence, such as the expression of proteins that regulate key pathways, like cGAS-STING (e.g., RECQL4, TRIM6), which may stratify patients who are likely to need additional innate immune agonists." (PMID 41295487, 2025). "However, functional loss of CHEK2 may be directly involved in potentiating the immune response through canonical inflammatory and anti-tumor pathways, acting through the cGAS-STING pathway." (PMID 40492861, 2025). "Tumor cells likewise exhibit formidable adaptive capacities to circumvent innate immune surveillance by releasing various immunosuppressive substances to reconfigure the tumor microenvironment and inhibit immune cell function, thus impeding activation of cGAS–STING–IFN-I signaling." (PMID 40470467, 2025). "Therefore, MEKi may enhance double-strand breaks after RT in a CHK2-dependent manner, which further augments the accumulation of double-strand DNA within tumor cells, thereby effectively activating the cGAS-STING pathway." (PMID 41368644, 2025). "Furthermore, exploring MB21D2's role in modulating tumor immunity through the cGAS-STING axis in immune-competent models may reveal new therapeutic strategies combining immune checkpoint inhibitors with Wnt pathway inhibitors." (PMID 40657359, 2025). "Therefore, cisplatin may induce tumor cells to activate endogenous cGAS-STING, which plays an anti-tumor role." (PMID 40918140, 2025). "Notably, the cGAS-STING pathway plays a crucial role in anti-tumor immunity 7,10,11." (PMID 40520004, 2025). "Furthermore, we showed that HMGCR inhibitors may enhance radiotherapy efficacy by boosting anti-tumor activity through further activation of the cGAS–STING pathway, which promotes the infiltration and function of CD8+ T cells." (PMID 40355720, 2025). "Notably, both radiotherapy and several cytotoxic regimens can dynamically up-regulate PD-L1 on tumor and immune cells through DNA-damage- and cGAS–STING/IFN-driven pathways, providing a biological rationale for combined chemo-/radio-immunotherapy with PD-1/PD-L1 inhibitors." (PMID 41463022, 2025). "However, whether and how the host cGAS–STING–IFN-I axis contributes to the anti-tumor effect of CTX in vivo remains unknown." (PMID 40227734, 2025). "Additionally, CIN-dependent cGAS–STING signaling activity may influence the tumor immune environment, particularly with regard to inflammatory cell infiltration, which may consequently influence the efficacy of EGFR-TKI therapy." (PMID 40136696, 2025). "Importantly, when tumor LRRC8C expression was high, endothelial STING expression was significantly higher in high tumor cGAS expression group versus low tumor cGAS expression group, indicating that tumor cGAS expression correlates with endothelial STING activation depending on LRRC8C." (PMID 38177099, 2024).
tumor (continued). "Nevertheless, several mechanisms are implemented by tumor cells to impair the activation and transduction of signaling at different levels, including DNA repair enhancement, and the regulation of the stability and activation of key components in the cGAS/STING pathway." (PMID 39621310, 2024). "Furthermore, we found that the treatment of tumor promoters, such as EGF or bFGF, shows a higher level of chromatin association of cGAS compared to the cGAS-S120A/T130A mutant, while the eluted cGAS from chromatin by NaCl addition was vice versa compared to remaining pellet fraction." (PMID 39424777, 2024). "Therefore, it is possible that the cGAS-STING pathway in DCs might be regulated by TGF-β within the tumor microenvironment." (PMID 38791963, 2024). "Additionally, miR-25-3p may influence the tumor microenvironment by modulating interactions between tumor cells and immune cells through impair cGAS-STING activity, further driving tumor growth and metastasis." (PMID 39407269, 2024). "We calculated the combination index of (G150 plus DOX) and (G150 plus ETO) to investigate whether the cGAS inhibitor could synergize with DOX or ETO to enhance tumor cell killing and observed a synergistic effect in both combination regimens (combination index <1)." (PMID 38145335, 2024). "Furthermore, our current findings suggest that the expression of tumor cell-intrinsic cGAS–STING, along with MMR/MSI status, could be a novel biomarker predicting the efficacy of immunotherapy using ICIs in GC." (PMID 39242811, 2024). "Research has indicated that T-MPs influence the immunogenic phenotype of DCs and produce potent anti-tumor immunity in processes of prevention and therapy by mediating antigen transfer from macrophages to DCs and inducing type I interferon production via the cGAS/STING pathway." (PMID 38512518, 2024). "The hybrid exosomes exhibited excellent tumor-targeting capabilities and prolonged circulation time, inducing polarization of tumor-associated macrophages to the M1 phenotype, releasing SN38 to cause DNA damage, and stimulating cGAS/STING activation with Mn2+ at the tumor site." (PMID 39450170, 2024). "However, following anti-PD-L1 antibody treatment, the tumor volume in WT mice was significantly reduced, while cGAS-deficient mice showed no significant change." (PMID 40018367, 2024). "In addition, when tumor cells are ingested by phagocytes, tumor DNA may escape the phagosomes and enter the cytoplasm to activate cGAS and its downstream molecules." (PMID 39445027, 2024). "Although the cGAS-STING pathway antagonists have the optimal beneficial effects on tumor diseases, prominent efforts are underway to develop novel compounds to control the severe inflammation and acute tissue damage observed from chronic stimulation by antagonizing cGAS and STING." (PMID 39113033, 2024). "In addition, there is an immune activation that is mediated by the liberation of manganese ions from the nanoparticles that can trigger the cGAS–STING pathway as a crucial immune biochemical cascade to foster the enlistment of immune cells to the tumor site, leading to an antitumor immune response." (PMID 39452584, 2024). "The cGAS-STING pathway in tumor cells has been linked to the activation of the innate immune system, local activation of antigen-presenting cells, recruitment of effector lymphocytes, and sensitization of the tumor microenvironment to immune checkpoint inhibitor therapy." (PMID 39487895, 2024). "Indeed, chronic cGAS-STING has been reported to promote tumor invasion and metastasis." (PMID 39050705, 2024). "Thus, cGAS is extremely important for the recognition of tumor cell DNA." (PMID 38525112, 2024). "Finally, combination nanotherapeutics based on the activation of the cGAS–STING signaling pathway have been used in tumor targeting therapy, including emerging strategies combining nanoformulated agonists with chemotherapy, radiotherapy, as well as other immunomodulation methods." (PMID 38525112, 2024).